MPDU1 (mannose-P-dolichol utilization defect 1)
Description:
Required for normal utilization of mannose-dolichol phosphate (Dol-P-Man) in the synthesis of N-linked and O-linked oligosaccharides and GPI anchors.
Synonyms: SL15; Lec35; PQLC5; CDGIf; SLC66A5; HBEBP2BPA; My008; PP3958
Tractability: Antibody: UniProt predicts a signal peptide or a membrane-spanning region. PROTAC: ubiquitination databases record sites on it; its protein half-life has been measured.
Gene: Protein-coding gene on chromosome 17 (7,583,529 to 7,592,789, forward strand). Ensembl gene ENSG00000129255.
Subcellular location: Membrane
Subcellular location (Human Protein Atlas): Endoplasmic reticulum; Mitochondria
Pathways (Reactome):
Disease: Defective MPDU1 causes CDG-1f
Metabolism of proteins: Biosynthesis of the N-glycan precursor (dolichol lipid-linked oligosaccharide, LLO) and transfer to a nascent protein
Gene Ontology:
Molecular function: protein binding
Biological process: oligosaccharide biosynthetic process; dolichol-linked oligosaccharide biosynthetic process; protein folding
Cellular component: endoplasmic reticulum; membrane; mitochondrion; endoplasmic reticulum membrane
Genetic constraint (gnomAD): Loss-of-function variants: 21 observed, 30.72 expected, observed/expected ratio (o/e) 0.68, 90% interval 0.48 to 0.98. The upper end of that interval is the gene's LOEUF score, 0.98, which puts it in group 4 of 6, group 1 being the genes least tolerant of losing a copy. Missense variants: 279 observed, 314.45 expected, observed/expected ratio (o/e) 0.89, 90% interval 0.8 to 0.98. Synonymous variants: 142 observed, 140.04 expected, observed/expected ratio (o/e) 1.01, 90% interval 0.88 to 1.17.
Gene-disease validity (ClinGen):
ClinGen rates the evidence that MPDU1 causes each of these diseases.
MPDU1-congenital disorder of glycosylation (autosomal recessive): Definitive. The CDG (Congenital Disorders of Glycosylation) syndromes are a group of autosomal recessive disorders affecting glycoprotein synthesis.
Homologues: Orthologues: chimpanzee MPDU1 (100% identical), macaque MPDU1 (99% identical), mouse Mpdu1 (91% identical), pig MPDU1 (91% identical), dog MPDU1 (89% identical), rabbit MPDU1 (87% identical), guinea pig MPDU1 (87% identical), rat Mpdu1 (74% identical), zebrafish mpdu1b (67% identical), tropical clawed frog mpdu1 (51% identical), Drosophila melanogaster CG3792 (47% identical), zebrafish mpdu1a (45% identical), and 1 more. Paralogues in human: SLC66A3 (22% identical).
Diseases named in the same sentence as MPDU1 in open-access papers:
MPDU1 is named in the same sentence as 13 diseases in open-access papers, as found by Europe PMC text mining. Sharing a sentence is not in itself a finding about the gene and the disease. The quoted sentences say what the papers report.
dystroglycanopathy (1 paper, 2019). "Here, we describe two patients with mutations in MPDU1, causing MPDU1‐CDG (CDG‐1f) with overlapping symptoms of CDG‐I and dystroglycanopathy." (PMID 31741824, 2019).
IgA nephropathy (1 paper, 2021). "rs4227 was found to be positively associated with IgA nephropathy in Han Chinese which located in 17p13 7431901 coding MPDU1 gene." (PMID 34248845, 2021).
MPDU1 also shares sentences with these, for which no sentence is quoted: epilepsy (3 papers); fructose intolerance (2); buphthalmos (1); congenital disorder of glycosylation (1); dilated cardiomyopathy (1); epileptic encephalopathies (1); galactosemia (1); glaucoma (1); inherited metabolic disorders (1); lymph node metastases (1); peroxisomal disease (1).